NOS2 (nitric oxide synthase 2)
Diseases named in the same sentence as NOS2 in open-access papers (continued):
Sharing a sentence is not in itself a finding about the gene and the disease.
fibrosis (1 paper, 2018). the formation of excess fibrous connective tissue in an organ or tissue in a reparative or reactive process. "The combination of low NOS2 expression to regulate relaxation and low HIF1A expression to regulate smooth muscle tone and contractility can potentially result in smooth muscle cramping and spasm, and subsequently to food getting stuck in the esophagus in a fibrosis-independent manner." (PMID 30455683, 2018).
Flavivirus Infections (1 paper, 2023). Infections with viruses of the genus FLAVIVIRUS, family FLAVIVIRIDAE. "NOS2, which was reported to play a major role in host protection in flavivirus infection, was highly expressed in EVTTS48." (PMID 37684223, 2023).
fracture (1 paper, 2017). "A PPI network was constructed with 167 nodes and 233 edges, and module analysis demonstrated that CCL2, CSF2, NOS2, and DLC1 may stimulate bone overgrowth after femoral fracture via anti-apoptosis-related functions." (PMID 28095896, 2017).
glomerulonephritis (1 paper, 2014). A renal disorder characterized by damage in the glomeruli. "Further diseases linked to PPROM were nephritis or glomerulonephritis (ACE, COL4A3, COL4A4, IGF1, NOS2, REN, TNF)." (PMID 25264875, 2014).
gonococcal infection (1 paper, 2024). "Our result is consistent with a previous report showing NOS2 induction following gonococcal infection in human FTOC." (PMID 38704381, 2024).
gout (1 paper, 2020). A condition characterized by painful swelling of the joints, which is caused by deposition of urate crystals. "Results showed that P47phox was significantly increased in gout-PMN-MDSCs compared to control-PMN-MDSCs, whereas the mRNA levels of arg-1 and NOS2 were not significantly affected." (PMID 33154749, 2020).
Harlequin ichthyosis (1 paper, 2024). Harlequin ichthyosis (HI) is the most severe variant of autosomal recessive congenital ichthyosis (ARCI; see this term). "For severe cases such as harlequin ichthyosis, inhibitors of nitric oxide synthase 2 (NOS2) or JAK are being explored to restore lipid barriers." (PMID 39022466, 2024).
HCMV infection (1 paper, 2020). "A recent case study described a previously healthy adult male with NOS2 deficiency who succumbed to HCMV infection despite evidence of previous common viral infections." (PMID 33323506, 2020). "Its importance against HCMV is highlighted by a recent clinical case describing an adult male with a NOS2 deficiency who died due to an active HCMV infection." (PMID 33323506, 2020). "HCMV infection of endothelial and smooth muscle cells induces NOS2 mRNA in an IE2-dependent manner." (PMID 33323506, 2020). "In contrast to lytic infection, nitric oxide produced during latent HCMV infection via NOS2 was demonstrated to be essential for viral latency by silencing of immediate early gene expression through an unknown mechanism." (PMID 33323506, 2020).
Hearing impairment (1 paper, 2025). A decreased magnitude of the sensory perception of sound. "The role of iNOS in preventing age-related cochlear degeneration was demonstrated in studies with Nos2-knockout mice, which exhibited early-onset hearing impairment." (PMID 40943337, 2025).
Heat Stroke (1 paper, 2025). A condition caused by the failure of body to dissipate heat in an excessively hot environment or during PHYSICAL EXERTION in a hot environment. "Previous studies have found that curcumin alleviates liver injury induced by heat stroke in a dose-dependent manner by down-regulating NF-κB, NOS2, and ICAM-1." (PMID 41430255, 2025).
Helicobacter infection (1 paper, 2023). "Accordingly, in vivo disruption of Slfn4 in Gli1CreERT2 x Slfn4fl/fl mice or pharmacologic inhibition by sildenafil after Helicobacter infection also suppressed SLFN4 and NOS2, reversed T cell suppression and mitigated SPEM development." (PMID 37334372, 2023).
hemarthrosis (1 paper, 2025). Bleeding into the joints. "During the acute phase (day 3), all M1 markers were elevated in response to hemarthrosis (Il6, Il1β, Nos2, Cxcl2 and Il1r1), whereby Il6 and Nos2 were suppressed to baseline levels by rhFVIII and mFcFVIII alike, without effects on Il1β, Cxcl2 and Il1r1." (PMID 40388523, 2025).
hepatoblastoma (1 paper, 2023). Hepatoblastoma (HB) is a malignant hepatic tumor and is the most common pediatric liver cancer. "Comparison between NOS2 and other hepatoblastoma biomarkers." (PMID 37795447, 2023).
histoplasmosis (1 paper, 2020). A disease caused by the fungus Histoplasma capsulatum. "In line with reduced NOS2 expression and NO2− production, we observed that survival of Il22−/− mice during histoplasmosis can be significantly extended by rIFN-γ treatment." (PMID 32517114, 2020).
infarction (1 paper, 2021). A localised pathological necrosis of tissue resulting from obstruction of the blood supply usually by a thrombus, an embolus, or vascular torsion. "Our correlation data, however, show that NOS2 expression in the peri-infarct cavity cortex is not correlated with infarction size and the severity of functional deficits." (PMID 33532129, 2021).
invasive ductal breast carcinoma (1 paper, 2015). The most common type of invasive breast carcinoma, accounting for approximately 70% of breast carcinomas. "Patient survival analysis demonstrated a correlation between increased NOS2 expression and worse survival at 5 years in patients with invasive ductal breast carcinoma (n = 79) (fold change 1.275, P = 0.037)." (PMID 25849745, 2015).
iris disease (1 paper, 2007). "Therefore, it is necessary to determine whether Nos2 genotype altered the iris disease or IOP profile." (PMID 18093296, 2007). "Slit lamp examination at various time points throughout the experiment showed that Nos2 genotype had no affect on the age of onset, progression, or severity of the iris disease (data not shown)." (PMID 18093296, 2007).
irritable bowel syndrome (1 paper, 2023). Irritable bowel syndrome (IBS) is a chronic functional condition of the lower gastrointestinal (GI) tract characterized by abdominal pain or discomfort and disordered bowel habit (diarrhea, constipation, or fluctuation between the two). "Using a systems pharmacology approach and molecular docking, the researchers investigated potential pathways for BXD treatment in the fight against irritable bowel syndrome (IBS) and predicted promising drug targets, such as PTGS2, NOS2, and PRSS1." (PMID 37836654, 2023).
lipoproteinosis (1 paper, 2014). "One possible explanation for the consistent macrophage morphology in DiNOS and Sftpd−/− mice, is that ablation of the NOS2 gene did not correct the lipoproteinosis observed with the loss of the Sftpd gene." (PMID 24465666, 2014).
lung injury (1 paper, 2015). "NOS2 is a determinant of pulmonary vascular blood flow, and nitric oxide production is increased in acute lung injury; we therefore explored whether exogenous NAM could affect Nos2 expression levels in the lung." (PMID 25875775, 2015). "Because nitric oxide levels are increased in the BAL fluid of patients with acute lung injury and because NAM has been reported to inhibit nitric oxide synthase 2 (NOS2) expression, we examined the effect of NAM on Nos2 mRNA levels." (PMID 25875775, 2015).
lupus nephritis (1 paper, 2022). Glomerulonephritis in the context of systemic lupus erythematosus. "Systemic inflammation associated with lupus nephritis induces an increase in Nos2 expression and reduces the levels of intrinsic inhibitors of Nos2 transcription in glomerular cells." (PMID 35740870, 2022). "Several murine and human studies have associated lupus nephritis with podocyte specific increase in NOS2 expression." (PMID 35740870, 2022).
lymph node metastasis (1 paper, 2022). "High expression of NOS2 is associated with decreased long-term survival and increased incidence of lymph node metastasis and lymphatic invasion." (PMID 35265525, 2022).
male infertility (1 paper, 2014). The inability of the male to effect fertilization of an ovum after a specified period of unprotected intercourse. "However, we did not found other four polymorphisms (NOS1 rs2682826, NOS1 rs1047735, NOS2 rs2297518, and NOS2 rs10459953) have any apparent relationship with risk of male infertility." (PMID 25517965, 2014). "Thus, the aim of the present study was to investigate the associations between five polymorphisms in NOS genes (NOS1 rs2682826, NOS1 rs1047735, NOS2 rs2297518, and NOS2 rs10459953, and NOS3 rs1799983) and male infertility risk and also sperm DNA damage in a Chinese population." (PMID 25517965, 2014).
malignant glioma (1 paper, 2017). A grade III or grade IV glioma arising from the central nervous system. "Of note, all primary cultures from malignant gliomas unable to generate neurospheres (GSC-) expressed low levels of NOS2, highlighting its possible relevance in glioma pathology as reported by other groups." (PMID 28424427, 2017).
malnutrition (1 paper, 2019). Inadequate nutrition resulting from poor diet, malabsorption, or abnormal nutrient distribution. "In animal models, malnutrition has been linked to reduced lymphocyte counts, as well as decreased expression of tumor necrosis factor (TNF), interferon-gamma (IFNγ), and nitric oxide synthase (NOS)-2 which are essential for generation of mycobactericidal nitrogen oxide." (PMID 30917170, 2019).
memory impairment (1 paper, 2024). "Notably, different to the results related to memory impairment and Aβ accumulation, the fluorescence intensity of NOS2 and Iba1 in the hippocampus slightly decreased after treatment with GW2580 alone." (PMID 38666910, 2024).
mesothelioma (1 paper, 2014). A usually malignant and aggressive neoplasm of the mesothelium which is often associated with exposure to asbestos. "Whether the unique capacity of mesothelial/mesothelioma tumor cells of synthesizing NOS2 is important to control a variety of infections in the pleural space in particular is unknown." (PMID 25192022, 2014).
metastatic cancers (1 paper, 2021). A carcinoma which has spread from the original site of growth to another anatomic site. "NOS2 upregulation was less and ASL downregulation was more pronounced in metastatic cancers." (PMID 34439753, 2021).
microcephaly (1 paper, 2021). A congenital or acquired developmental disorder in which the circumference of the head is smaller than normal for the person's age and sex. "In this study, we reported an interesting association of alleles and haplotypes of NOS2, VEGFA, and TNF genes with the CZS development and severity of the microcephaly in the CZS." (PMID 33672623, 2021). "Our findings showed higher risk of CZS due ZIKV infection in the first trimester and suggested that polymorphisms in NOS2 and TNF genes affect the risk of CZS and severe microcephaly." (PMID 33672623, 2021).
mood disorder (1 paper, 2025). A cognitive disorder a disturbance in which the person's mood is hypothesized to be the main underlying feature. "Bioinformatic analyses revealed enrichment in pathways related to neurodegeneration and mood disorders, identifying key targets such as IL‐6, MAPK, and NOS2." (PMID 40212473, 2025).
mucositis (1 paper, 2022). Mucositis is inflammation and damage of the mucous membranes lining the mouth and other parts of the gastrointestinal (GI) tract. "Its anti-mucositis effect may be through regulating TNF/NF-κB pathway and inhibiting inflammatory mediators PTGS2 and NOS2." (PMID 36278232, 2022).
Multiple Organ Failure (1 paper, 2025). A progressive condition usually characterized by combined failure of several organs such as the lungs, liver, kidney, along with some clotting mechanisms, usually postinjury or postoperative. "1823C>T (p.Ser608Leu, rs2297518), may enhance NOS2 gene expression, exacerbating endothelial dysfunction and contributing to critical septic complications such as hypotension and multiple organ failure (MOF)." (PMID 41226345, 2025).
Mycobacterium infection (1 paper, 2011). Infections with bacteria of the genus Mycobacterium. "Other studies in the murine model of infection involving iNOS inhibitors or mice with disruption in the gene nos2 highlighted the crucial role played by RNI in host defence against Mycobacterium infection." (PMID 21760796, 2011).
myelitis (1 paper, 2023). An inflammatory process affecting the spinal cord. "H&E staining of the spinal cord sections showed higher myelitis in infected NOS2-/- mice as compared to WT controls (black arrows)." (PMID 36966345, 2023).
myopia (1 paper, 2024). "Following myopia induction for 4 weeks (P<0.001), NOS2 gene expression was lower in the ZJP group compared to the LIM group." (PMID 39625993, 2024). "Therefore, we regard NOS2, LPCAT1, and CHRNA7 as the core targets of ZJP for anti-myopia." (PMID 39625993, 2024).
neurocysticercosis (1 paper, 2015). "Here, we show that microglia display a diminished expression of M1-inflammatory mediators such as tumor necrosis factor-alpha (TNF-α), interleukin-6 (IL-6), and nitric oxide synthase 2 (NOS2) in murine neurocysticercosis." (PMID 26148848, 2015).
ocular toxoplasmosis (1 paper, 2010). Ocular toxoplasmosis is an infection in the eye caused by the parasite, Toxoplasm a gondii. "Moreover, mice with diminished expression of Beclin 1 and mice with inactivation of Atg7 in microglia/macrophages are susceptible to cerebral and ocular toxoplasmosis despite upregulation of IFN-γ, TNF-α and NOS2 as well as the induction of T cell-mediated immunity." (PMID 21217818, 2010).
ovarian serous adenocarcinoma (1 paper, 2013). An adenocarcinoma that arises from the ovary and is characterized by the presence of malignant epithelial cells that, in well differentiated tumors, resemble the epithelium of the fallopian tube or, in poorly differentiated tumors, show anaplastic features and marked nuclear atypia. "It should be noted that papillary growth, a clear character in ovarian serous adenocarcinoma from which NOS2 and NOS2TR were isolated, was detected." (PMID 24367486, 2013).
ovarian tumor (1 paper, 2020). "Here, an increased mRNA levels of NOS‐2 suggest an increase in tumor‐infiltrated immune population that is a source of this NOS‐2 that plays a role in delaying the ovarian tumor growth." (PMID 32797726, 2020).
papilloma (1 paper, 2020). A benign epithelial neoplasm that projects above the surrounding epithelial surface and consists of villous or arborescent outgrowths of fibrovascular stroma. "Elevated NO and arginase activity in the mSCC38 model was consistent with our finding that transcription of Nos2 and Arg1 was increased in neutrophils from tumors and papillomas of DMBA/PMA-treated mice, compared to surrounding skin." (PMID 32664318, 2020).
periapical periodontitis (1 paper, 2024). Inflammation of the periapical tissue. "Polymorphisms in the NOS2 and SOCS1 genes influenced the OHRQoL of patients undergoing root canal treatment in teeth with asymptomatic periapical periodontitis." (PMID 38537022, 2024). "Therefore, in this study, we evaluated whether genetic polymorphisms in IL1A, IL10, IL1RN, NOS2, and SOCS1 genes are potential biomarkers for OHRQoL in patients undergoing root canal treatment in teeth with asymptomatic periapical periodontitis." (PMID 38537022, 2024).
periodontal disease (1 paper, 2017). "Nevertheless, further studies with larger sample and ethnically different populations, as well as meta-analysis approaches, are needed to better evaluate the potential association of polymorphisms in the NOS2 gene and its influence on NO production in the development of periodontal disease." (PMID 28617311, 2017).
prostatic adenocarcinomas (1 paper, 2017). "In a model of human prostatic adenocarcinomas, only concomitant inhibition of arginase 1 and NOS2 reduces PNT production and recovers tumor-infiltrating lymphocyte antitumor responsiveness." (PMID 28223985, 2017).
psoriatic arthritis (1 paper, 2023). Joint inflammation associated with psoriasis. "In this context, mannan-induced Nos2 in macrophages was shown to have a prominent role in enhancing IL-17 promoted psoriatic arthritis by innate immune cells." (PMID 36645209, 2023).
Q fever (1 paper, 2023). A bacterial infection caused by Coxiella burnetii. "Notably, the effect of deletion of Acod1 on C. burnetii replication was much stronger than the impact of deficiencies of several other IFNγ‐induced antimicrobial defense mechanisms (NOS2, IDO1/2, GBPs), thus establishing ACOD1 as a major protective determinant in the host defense against Q fever." (PMID 36479617, 2023).
sarcoidosis (1 paper, 2025). Sarcoidosis is a multisystemic disorder of unknown cause characterized by the formation of immune granulomas in involved organs. "Although the mechanisms linking NOS2 and cardiac involvement remain unclear, the upregulation of NOS2 in sarcoidosis may be related to the promotion of granuloma formation in inflammatory states." (PMID 41463010, 2025).
serous adenocarcinoma (1 paper, 2013). An adenocarcinoma that is characterized by the presence of papillary patterns and cellular budding. "In subcutaneous tumors formed by the inoculation of NOS2TR cells, we noted the same histological appearance identical to serous adenocarcinoma and central necrosis although it was lesser extent to those of parental NOS2 cells." (PMID 24367486, 2013).
skin infectious diseases (1 paper, 2018). "Since more severe lesions from both SP and ATL presented an important concentration of neutrophils, or CD8+ T cells and NOS2 expression, respectively, our results also suggest that, unbalanced host SIS - parasite relationship can lead to more severe manifestations of skin infectious diseases." (PMID 29440688, 2018).
skin tumors (1 paper, 2012). "IFNγR1 and inducible nitric oxide synthase-2 (NOS2) expression in recipient mice were also required for tumor regression which indicated that CTL-expressed-IFNγ targeted host cells to eliminate skin tumors." (PMID 23060881, 2012).
Splenomegaly (1 paper, 2018). Abnormal increased size of the spleen. "As expected, Nos2−/− mice developed dramatic macroscopic lung and spleen pathology after M.tb infection, with numerous large lung granulomatous lesions and splenomegaly." (PMID 30573728, 2018).
subarachnoid haemorrhage (1 paper, 2013). "For instance, aminoguanidine inhibition of NOS2 activity ameliorates cerebral vasospasm after subarachnoid haemorrhage in rabbits via increase of NOS1 mRNA and protein levels." (PMID 23951240, 2013).
synovitis (1 paper, 2023). Inflammation of a synovial membrane. "When applying histopathological scorings on 2-y–old wildtype (WT) and Nos2−/− mice, we observed that Nos2−/− mice exhibited less signs of OA compared to WT animals, with reduced cartilage erosion and synovitis severity." (PMID 37428931, 2023). "While half of the 2-y–old WT mice displayed severe cartilage loss and signs of synovitis, none of the examined Nos2−/− mice had such symptoms, indicating that Nos2 and NO play a significant role in the induction and/or progression of age-related OA." (PMID 37428931, 2023).
T-cell deficiency (1 paper, 2019). "Although NOS2 expression is characteristically elicited by IFNγ-induced activation of STAT1-dependent gene transcription, expression of this cytokine was not affected by ChAT T-cell deficiency." (PMID 30973939, 2019).
tauopathy (1 paper, 2021). Neurodegenerative disorders involving deposition of abnormal tau protein isoforms (tau proteins) in neurons and glial cells in the brain. "Hippocampi and amygdalae from 3x Tg-AD linalool-treated mice also showed a large reduction in extracellular β-amyloidosis, tauopathy, astrogliosis, and microgliosis, as well as pro-inflammatory marker levels of p38 MAPK, NOS2, COX2 and IL-1β." (PMID 33669787, 2021).
Tendon rupture (1 paper, 2023). Breakage (tear) of a tendon. "However, additional studies on neuro-glial interactions are essential to understand the exact mechanism involved in acute and chronic pain induced by Achilles tendon rupture since neurons are also able to express NOS-2 and COX-2." (PMID 37851789, 2023).